SLC12A3 (solute carrier family 12 member 3)
Diseases named in the same sentence as SLC12A3 in open-access papers (continued):
Sharing a sentence is not in itself a finding about the gene and the disease.
type 2 diabetes (9 papers, 2014 to 2025). "In addition, several population genetic association studies have indicated that the single nucleotide variant Arg913Gln in the SLC12A3 gene is associated with diabetic kidney disease in type 2 diabetes subjects." (PMID 35591852, 2022). "In addition, the gene variants in the SLC12A3 have been reported as a genetic susceptibility factor of cardiovascular diseases such as type 2 diabetes." (PMID 31480784, 2019). "Furthermore, a previous case-control study also reported that the SLC12A3-Arg913Gln variation could be used to predict the risk of ESRD in Chinese patients with type 2 diabetes." (PMID 35801212, 2022). "Furthermore, the single nucleotide variant (SNV) Arg913Gln in the SLC12A3 gene is found to be associated with DKD in type 2 diabetes (T2D) subjects." (PMID 35591852, 2022). "In a large cohort of patients with type 2 diabetes mellitus the SLC12A3 gene was identified as a candidate gene for conferring susceptibility to diabetic nephropathy, and that the substitution of Arg913 to Gln might be associated with reduced progression of nephropathy." (PMID 25157616, 2014).
diabetic nephropathy (8 papers, 2014 to 2025). "That is the reason why this systematic review was focused on identifying studies that associated the Arg913Gln variation of SLC12A3 gene with the diabetic nephropathy in T2DM and GS." (PMID 31660880, 2019). "In this systematic review, the association of the Arg913Gln variation of SLC12A3 gene with diabetic nephropathy in individuals with T2DM and GS was explored." (PMID 31660880, 2019). "In regard to this variation of SLC12A3 gene in T2DM-individuals with diabetic nephropathy, this systematic review found a genetic association in most the studies included." (PMID 31660880, 2019). "The present systematic review provides evidence to support that the Arg913Gln variation of SLC12A3 gene is associated with the diabetic nephropathy in individuals with T2DM and GS." (PMID 31660880, 2019). "The results showed in this systematic review contribute to better understanding of the association between the Arg913Gln variation of SLC12A3 gene with the pathogenesis of diabetic nephropathy in individuals with T2DM and GS." (PMID 31660880, 2019). "In an important way, it should be noted that a meta-analysis has studied the SLC12A3 gene in association with diabetic nephropathy in T2DM." (PMID 31660880, 2019). "Several studies have reported a link between SLC12A3 gene variants and diabetic nephropathy." (PMID 35801212, 2022). "SLC12A3 (solute carrier family 12 member 3) gene variants are associated with diabetic nephropathy; however, their association with hypertensive nephropathy remains unknown." (PMID 35801212, 2022). "Similarly, two case-control studies also reported that SLC12A3-Arg913Gln variation was significantly associated with diabetic nephropathy in the Indian population." (PMID 35801212, 2022). "This review shows a significant genetic association in most studies in the Arg913Gln variation of SLC12A3 gene with the diabetic nephropathy, pointing out that the mutations of this gene could be a key predictor of end-stage renal disease." (PMID 31660880, 2019). "Additionally, these studies reported that the minor allele 913Gln in the SLC12A3 gene could have a protective genetic effect against the development and/or progression of diabetic nephropathy for these populations (p < 0.01)." (PMID 31660880, 2019). "This in silico outcome is consistent with observations from in vivo experiments, where granular cells of the glomerular apparatus suffered from diabetic kidney disease showed diminished expression of Slc12a3." (PMID 40106407, 2025). "The analysis revealed that deleting the gene Slc12a3 from normal kidney cells brought the cells closest to those of diabetic kidney disease, with a cosine similarity of 0.018." (PMID 40106407, 2025). "In Malays, SLC12A3 Arg913Gln polymorphism and ICAM1 K469E (A/G) polymorphism were found to be associated with diabetic nephropathy." (PMID 37187702, 2023). "The roles of SLC12A3 in kidney development and progression of diabetic nephropathy were further supported by animal studies in db/db mice and zebrafish." (PMID 35801212, 2022). "It is possible that the roles of SLC12A3 in the progression of diabetic nephropathy are influenced by genetic differences." (PMID 35801212, 2022). "Although the SLC12A3 gene was found to be associated with diabetic nephropathy in some studies, the findings were not consistent with those of other studies." (PMID 35801212, 2022). "In both studies none polymorphisms in SLC12A3 gene (including the Arg913Gln variation) were associated with diabetic nephropathy." (PMID 31660880, 2019).
chronic kidney disease (7 papers, 2019 to 2024). Impairment of the renal function secondary to chronic kidney damage persisting for three or more months. "SLC12A3 contributes to genetic susceptibility to DKD, with its polymorphisms associated with end-stage renal disease." (PMID 39590877, 2024). "SLC12A3 contributes to genetic susceptibility to DKD, and its polymorphisms are associated with end-stage renal disease." (PMID 39590877, 2024).
Obesity (5 papers, 2015 to 2025). Accumulation of substantial excess body fat. "The polymorphisms of ACE, SLC12A3 and CYP11β-2 showed a gender difference in the interaction of sodium intakes and obesity." (PMID 25768006, 2015). "The obesity risk increased in the boys with the GRK4 A486V, ACE and SLC12A3 mutant and in girls with CYP11β-2 mutant and GRK4 A486V hetero type as they increased the residual-Na." (PMID 25768006, 2015). "The obesity risk increased 7.06, 16.8, and 46.09-fold more in boys with GRK4 A486V, ACE, and SLC12A3 mutants as sodium intake increased." (PMID 25768006, 2015). "The obesity risk increased with GRK4 A486V, ACE, and SLC12A3 variants in boys, whereas it increased with GRK4 A486V and CYP11B2 variants in girls as sodium intake increased." (PMID 25768006, 2015). "For example, boys with GRK4 A486V, ACE, and SLC12A3 mutants and girls with GRK4 A486V hetero and CYP11β-2 mutant may reduce their daily sodium intake as if they want to reduce the prevalence of obesity." (PMID 25768006, 2015).
renal tubular disorder (5 papers, 2017 to 2025). "It is an inherited renal tubular disorder resulting from mutations in the SLC12A3 gene, which encodes the thiazide-sensitive sodium-chloride cotransporter (NCCT) in the distal convoluted tubule (DCT) of the kidneys." (PMID 40777730, 2025).
kidney stones (3 papers, 2019 to 2025). "The second younger brother of the proband harbored the same simultaneous mutations in SLC12A3 and CLCNKB and exhibited similar clinical features except normomagnesemia and bilateral kidney stones." (PMID 33807568, 2021).
lung carcinoma (3 papers, 2020 to 2024). "SLC12A3 may contribute to the radio-resistance of lung cancer." (PMID 38373964, 2024).
Andermann syndromes (2 papers, 2021 to 2024). "The SLC12 family is a nine-member gene family with three established associated human diseases: SLC12A1 (MIM No. 600839), SLC12A3 (MIM No. 600968), and SLC12A6 (MIM No. 604878), which cause Bartter, Gitelman, and Andermann syndromes, respectively." (PMID 34226616, 2021).
atherosclerosis (2 papers, 2020 to 2023). A disease characterized by the build-up of fatty material and calcium deposition in the arterial wall resulting in partial or complete occlusion of the arterial lumen. "Several other TG-affected genes showed weaker associations with atherosclerosis-related outcomes (ABCG1, AC004791.2, CPA3, CYP11A1, SLC12A3) or rheumatoid arthritis (GATA2, SMPDL3A) but were no longer statistically significant after correction for multiple testing (PFDR > 0.05)." (PMID 36725846, 2023).
autoimmune disease (2 papers, 2017 to 2018). A disorder resulting from loss of function or tissue destruction of an organ or multiple organs, arising from humoral or cellular immune responses of the individual to their own tissue constituents. "In the diagnosis of GS in patients with autoimmune disease, genetic testing of SLC12A3 is essential for differentiating the two forms." (PMID 28819721, 2017). "Although several cases of acquired GS associated with autoimmune disease have been described, some of them lacked a genetic test of SLC12A3 in diagnosing the acquired GS." (PMID 28819721, 2017).
cardiomyopathy (2 papers, 2020 to 2022). A disease of the heart muscle or myocardium proper. "GSshould be distinguished from other diseases such as KICA syndrome (Kidneytubulopathy and Cardiomyopathy) and Gitelman-like syndrome which areunrelated to SLC12A3 mutations." (PMID 39076641, 2022).
Hashimoto thyroiditis (2 papers, 2021 to 2023). An autoimmune disorder caused by the production of autoantibodies against thyroid tissue. "Moreover, gene analysis revealed his mother diagnosed with subclinical hypothyroidism due to Hashimoto’s thyroiditis carried the c.506-1G > A heterozygous mutation in the SLC12A3 gene and his father carried the c.1456G > A heterozygous mutation in the SLC12A3 gene." (PMID 37131142, 2023).
hypertensive nephropathy (2 papers, 2022 to 2023). Kidney damage that results from chronically elevated blood pressure; complications include glomerular damage resulting in proteinuria and hematuria. "However, the association between genetic variations in SLC12A3 and hypertensive nephropathy remains unknown." (PMID 35801212, 2022).
breast carcinoma (1 paper, 2022). "Colocalization analysis provided little support for NCC and ER− breast cancer association sharing a causal variant within the SLC12A3 locus (11.5% posterior probability of a shared causal variant)." (PMID 35113855, 2022).
epilepsy (1 paper, 2023). A brain disorder characterized by episodes of abnormally increased neuronal discharge resulting in transient episodes of sensory or motor neurological dysfunction, or psychic dysfunction. "We report a rare case of GS with homozygous loss of SLC12A3 presenting with epilepsy." (PMID 40217495, 2023).
Familial hypocalciuric hypercalcemia type 1 (1 paper, 2025). "Genetic testing revealed a novel heterozygous CASR p.Tyr161* mutation and a homozygous SLC12A3 p.Thr60Met mutation, which ultimately confirmed the diagnosis of familial hypocalciuric hypercalcemia type 1 (FHH1) combined with GS." (PMID 40070587, 2025).
fibrosarcoma (1 paper, 2024). A malignant mesenchymal fibroblastic neoplasm affecting the soft tissue and bone. "Consistent results were observed in xenograft growth assays, and HCTZ treatment alone and knockdown of SLC12A3 promoted human fibrosarcoma growth." (PMID 38373964, 2024).
Hyperglycemia (1 paper, 2020). An increased concentration of glucose in the blood. "However, diagnosis of hyperglycemia in GS patients has not been thoroughly investigated, and family studies on SLC12A3 mutations and glucose metabolism are rare." (PMID 32702863, 2020).
hypertriglyceridemia (1 paper, 2019). A laboratory test result indicating elevated triglyceride concentration in the blood. "The rs11643718 in the solute carrier family 12 member 3 (SLC12A3) is another newly found SNP associated with hypertriglyceridemia." (PMID 31480784, 2019).
sarcoma (1 paper, 2024). A usually aggressive malignant neoplasm of the soft tissue or bone. "Additionally, by using the GEPIA2 web tool, the poor prognosis of sarcoma patients showed a close association with the high expression of SLC12A3." (PMID 38373964, 2024). "In this research, low expression of SLC12A3 was associated with a worse prognosis in sarcoma." (PMID 38373964, 2024). "Analysis of Gene Expression Omnibus(GEO) data (GSE21122) showed that SLC12A3 is lower in sarcoma tissues than in normal tissues." (PMID 38373964, 2024).
kidney disease (11 papers, 2014 to 2025). "This has implicated that the SLC12A3 gene may have important genetic effects in renal diseases." (PMID 35591852, 2022). "An experimental study has previously showed that with knockdown of zebrafish ortholog, slc12a3 led to structural abnormality of kidney pronephric distal duct at 1-cell stage, suggesting that SLC12A3 may have genetic effects in renal disorders." (PMID 35591852, 2022).
genetic diseases (9 papers, 2018 to 2025). "Although the reason for this discrepancy is unknown, we recommend whole-exome or whole-genome sequencing for patients with GS to identify undiscovered variations in SLC12A3, which may increase the identification rate for genetic diseases such as GS." (PMID 33996672, 2021).
tumor (4 papers, 2020 to 2024). "The comparatively lower expression of AGXT, PTGER3 and SLC12A3 in tumours correlates with worse prognosis in KIRC patients, while higher expression of ALOX5 predicts reduced survival." (PMID 32144299, 2020). "We identified three genes (AGXT, PTGER3 and SLC12A3) with lower mRNA levels in tumour samples, and patients with a high expression of these three genes exhibited prolonged survival." (PMID 32144299, 2020). "It is difficult to determine whether SLC12A3 plays a role in the promotion of tumor progression by HCTZ." (PMID 38373964, 2024). "Notably, HCTZ significantly promoted tumor growth by regulating SLC12A3 and weakening the therapeutic effect of PD1ab." (PMID 38373964, 2024). "The role of SLC12A3 in tumor progression still largely needs to be explored." (PMID 38373964, 2024). "Furthermore, we preliminarily found that HCTZ may promote tumor progression through SLC12A3." (PMID 38373964, 2024). "Consistently, we found that ALOX5 was upregulated in the tumour samples, while AGXT, PTGER3, and SLC12A3 were downregulated in the tumour samples." (PMID 32144299, 2020). "For instance, using WGCNA and a protein-protein interaction network, a recent study analyzed the gene expression pattern of 26 pairs of tumor tissues/adjacent tissues and identified four hub genes involved in the progression of KIRC, including AGXT, PTGER3, SLC12A3, and ALOX5." (PMID 33110456, 2020). "SLC12A3 Positively correlates with both CD8+ and CD4+ T cells and dendritic cells, pointing to its involvement in enhancing T cell-mediated immunity and antigen presentation, which could be crucial for anti-tumor responses in ccRCC." (PMID 39348357, 2024). "By successful knockdown of SLC12A3, HCTZ did not exhibit the promoting effect on the tumor in vivo and in vitro." (PMID 38373964, 2024). "When SLC12A3 was knocked down, HCTZ treatment did not improve tumor promotion." (PMID 38373964, 2024).
cardiovascular disease (3 papers, 2018 to 2019). "Increasing evidences from GWAS studies and association tests suggested SLC12A3 gene which encodes Na-Cl cotransporter, as a candidate gene for human cardiovascular disease via affecting blood pressure." (PMID 29661184, 2018). "In this study, we investigated functional relationship between three protein-coding genes genetically associated with cardiovascular disease, i.e., CDH13, SLC12A3, and CKAP5, and their intronic miRNAs using a data-driven approach." (PMID 31464655, 2019).
infectious disease (1 paper, 2023). A disorder directly resulting from the presence and activity of a microbial, viral, or parasitic agent in humans. "Giltelman syndrome (GS) is an autosomal recessive infectious disease, which is caused by the mutation of SLC12A3 gene encoding thiazide diuretic sensitive sodium chloride cotransporter located in the distal convoluted tubule of the kidney." (PMID 37058043, 2023).
SLC12A3 also shares sentences with these, for which no sentence is quoted: Hyperkalemia (32 papers); pseudohypoaldosteronism type 2 (19); Gordon syndrome (17); diabetes (8); metabolic acidosis (6); metabolic syndrome (6); Alkalosis (5); Nephropathy (5); Polyuria (5); Hyperinsulinemia (4); Hyponatremia (4); kidney (4); renal failure (4); cancer (3); end-stage renal disease (3); hyperaldosteronism (3); Hypocalcemia (3); potassium deficiency (3); primary aldosteronism (3); Zinc deficiency (3); Acidosis (2); blood pressure (2); Cushing syndrome (2); cystic kidneys (2); diabetes insipidus (2); EAST syndrome (2); electrolyte disorder (2); Glucose intolerance (2); Hypernatremia (2); Insulin resistance (2).
A further 60 diseases each share a sentence with SLC12A3 in 2 papers or fewer.